ARHGAP44 (Rho GTPase activating protein 44)
Description:
GTPase-activating protein (GAP) that stimulates the GTPase activity of Rho-type GTPases. Thereby, controls Rho-type GTPases cycling between their active GTP-bound and inactive GDP-bound states. Acts as a GAP at least for CDC42 and RAC1. In neurons, is involved in dendritic spine formation and synaptic plasticity in a specific RAC1-GAP activity (By similarity). Limits the initiation of exploratory dendritic filopodia. Recruited to actin-patches that seed filopodia, binds specifically to plasma membrane sections that are deformed inward by acto-myosin mediated contractile forces. Acts through GAP activity on RAC1 to reduce actin polymerization necessary for filopodia formation (By similarity). In association with SHANK3, promotes GRIA1 exocytosis from recycling endosomes and spine morphological changes associated to long-term potentiation (By similarity).
Synonyms: RICH-2; KIAA0672; RICH2; NPC-A-10
Tractability: Antibody: its Gene Ontology location is reachable by antibodies, with medium confidence. PROTAC: its protein half-life has been measured.
Gene: Protein-coding gene on chromosome 17 (12,789,498 to 12,991,643, forward strand). Ensembl gene ENSG00000006740.
Subcellular location: Cell projection, dendritic spine; Recycling endosome; Presynapse; Cell projection, dendrite
Pathways (Reactome):
Signal Transduction: CDC42 GTPase cycle; RAC1 GTPase cycle; RHOA GTPase cycle
Gene Ontology:
Molecular function: phospholipid binding; protein binding; GTPase activator activity; small GTPase binding
Biological process: negative regulation of filopodium assembly; negative regulation of Rac protein signal transduction; regulation of actin cytoskeleton organization; regulation of dendritic spine morphogenesis; regulation of GTPase activity; regulation of small GTPase mediated signal transduction; modification of postsynaptic structure; modulation of chemical synaptic transmission; regulation of neurotransmitter receptor transport, endosome to postsynaptic membrane; signal transduction
Cellular component: leading edge membrane; cytosol; dendrite; dendritic spine; plasma membrane; postsynaptic density; presynapse; presynaptic active zone; recycling endosome; cytoplasm; glutamatergic synapse; postsynapse
Genetic constraint (gnomAD): Loss-of-function variants: 40 observed, 86.13 expected, observed/expected ratio (o/e) 0.46, 90% interval 0.36 to 0.61. The upper end of that interval is the gene's LOEUF score, 0.61, which puts it in group 2 of 6, group 1 being the genes least tolerant of losing a copy. Missense variants: 858 observed, 985.85 expected, observed/expected ratio (o/e) 0.87, 90% interval 0.82 to 0.92. Synonymous variants: 434 observed, 387.69 expected, observed/expected ratio (o/e) 1.12, 90% interval 1.03 to 1.21.
Homologues: Orthologues: chimpanzee ARHGAP44 (99% identical), rabbit ARHGAP44 (95% identical), macaque ARHGAP44 (95% identical), dog ARHGAP44 (94% identical), rat Arhgap44 (94% identical), mouse Arhgap44 (94% identical), pig ARHGAP44 (92% identical), guinea pig ARHGAP44 (79% identical), tropical clawed frog arhgap44 (77% identical), zebrafish arhgap44a (69% identical), zebrafish arhgap44b (63% identical), Drosophila melanogaster RhoGAP92B (25% identical), and 1 more. Paralogues in human: ARHGAP17 (48% identical), SH3BP1 (35% identical).
Diseases named in the same sentence as ARHGAP44 in open-access papers:
ARHGAP44 is named in the same sentence as 18 diseases in open-access papers, as found by Europe PMC text mining. Sharing a sentence is not in itself a finding about the gene and the disease. The quoted sentences say what the papers report.
osteosarcoma (2 papers, 2012 to 2023). A usually aggressive malignant bone-forming mesenchymal neoplasm, predominantly affecting adolescents and young adults. "KM survival analysis (GSE39058) indicated that ARHGAP44 expression in osteosarcoma was associated with prognosis." (PMID 38031136, 2023). "Immunohistochemical staining of 21 clinically collected osteosarcoma tissue specimens and western blotting results demonstrated high ARHGAP44 expression in osteosarcoma tissues." (PMID 38031136, 2023). "The downregulation of ARHGAP44 expression reduced the malignant biological behavior of osteosarcoma cells." (PMID 38031136, 2023). "The median survival times of patients with osteosarcoma exhibiting high and low expression of ARHGAP44 were 4.4 and 9.3 years, respectively, and the difference was statistically significant (p = 0.0291)." (PMID 38031136, 2023). "The expression level of ARHGAP44 in osteosarcoma and its relationship with tumor prognosis were detected using Gene Expression Omnibus database analysis and immunohistochemical staining of clinical specimens." (PMID 38031136, 2023). "CCK-8, clone formation, transwell invasion, wound healing, and flow cytometry assays showed that downregulation of ARHGAP44 expression significantly reduced the malignant biological behavior of osteosarcoma cells." (PMID 38031136, 2023). "In the present study, we investigated the effects of the RhoGAP family member ARHGAP44 on the malignant biological behavior of osteosarcoma cells." (PMID 38031136, 2023). "The GEO database analysis (GSE14359) showed that the expression level of ARHGAP44 in osteosarcoma was significantly higher than that in normal tissues (p = 0.011)." (PMID 38031136, 2023). "Therefore, this study aimed to investigate the biological function of ARHGAP44 in osteosarcoma and its possible application as a therapeutic target." (PMID 38031136, 2023). "This suggests that ARHGAP44 affects osteosarcoma cell invasion." (PMID 38031136, 2023). "ARHGAP44 expression in osteosarcoma tissues was significantly higher than that in normal tissues." (PMID 38031136, 2023). "In addition, the immunohistochemistry results of osteosarcoma tumor specimens and paracancerous tissues showed that the expression of ARHGAP44 was higher in osteosarcoma tissues than in paracancerous tissues." (PMID 38031136, 2023). "ARHGAP44 was highly expressed in osteosarcoma and was negatively correlated with its prognosis." (PMID 38031136, 2023). "Biogenic analysis showed that ARHGAP44 was highly expressed in osteosarcoma." (PMID 38031136, 2023). "This suggests that ARHGAP44 may play a pro-carcinogenic role in osteosarcoma and may be used as a clinical marker for osteosarcoma prognosis." (PMID 38031136, 2023).
osteosarcoma (continued). "In addition, KM survival analysis using both bioinformatic analysis and clinical specimens collected suggested that high ARHGAP44 expression was negatively correlated with the prognosis of osteosarcoma." (PMID 38031136, 2023). "Western blotting showed that ARHGAP44 expression in MG63 and HOS osteosarcoma cells was higher than that in hFOB1.19 osteoblastic cells (p < 0.05)." (PMID 38031136, 2023). "When the expression of ARHGAP44 was downregulated, the migratory ability of MG63 and HOS osteosarcoma cell lines was significantly attenuated compared with the control group (p < 0.01)." (PMID 38031136, 2023). "Results of the transwell invasion and wound healing assays suggested that the downregulation of ARHGAP44 expression could inhibit the invasion and migration of MG63 and HOS osteosarcoma cells." (PMID 38031136, 2023).
adenoma (1 paper, 2022). A neoplasm arising from the epithelium. "Six predicted Mir34a targets (Arhgap44, Ccnjl, Clec16a, Esyt3, Golga7b, Grap) were up-regulated in both Mir34a-deficient adenomas and tumoroids." (PMID 36147476, 2022).
leishmaniasis (1 paper, 2023). Infectious disease that is transmitted through the bite of hematophagous female phlebotomine sand flies. "Thus, both Arhgap44 and Aloxe3 have the potential to modify susceptibility to leishmaniasis, but none of them exhibited differential expression in the skin or spleen." (PMID 37600780, 2023).
cancer (3 papers, 2021 to 2026). A tumor composed of atypical neoplastic, often pleomorphic cells that invade other tissues. "Furthermore, ARHGAP44 gene was associated with multiple critical cancer traits including cancer stemness, cytoskeleton dynamics as well as immune infiltration in different human cancer types." (PMID 41988127, 2026). "Then, genetic alteration analysis revealed that ARHGAP44 expression varies in human cancers, which was partly due to the modulation by DNA methylation and phosphorylation." (PMID 41988127, 2026). "Furthermore, the probable reasons for the aberrant changed expression of ARHGAP44 in cancers compared to corresponding normal control samples were investigated." (PMID 41988127, 2026). "However, ARHGAP44 gene, a member of GAP proteins that regulate the Rho GTPases cycling between their active GTP-bound and inactive GDP-bound states, remains poorly understood in terms of its role in cancer development." (PMID 41988127, 2026).
tumor (2 papers, 2023 to 2024). "ARHGAP44 is a member of the RhoGAP family, and loss of RhoGAP activity often leads to uncontrolled GTPase activity, which subsequently affects tumor progression." (PMID 38031136, 2023). "Similarly, KM survival analysis based on clinical specimen data showed that high ARHGAP44 expression was associated with tumor prognosis (p = 0.0495)." (PMID 38031136, 2023). "Through an extensive review, we found that ARHGAP27 and ARHGAP44 are hardly relevant in tumour research." (PMID 39075640, 2024). "In this study, we analyzed the potentially relevant tumor signaling pathways of ARHGAP44 using the TCGA database." (PMID 38031136, 2023). "Additionally, Kaplan–Meier analysis of clinical specimens suggested that ARHGAP44 was negatively correlated with tumor prognosis." (PMID 38031136, 2023).
cardiovascular diseases (1 paper, 2024). "The ARHGAP44 gene has also been reportedly associated with cardiovascular diseases, serum creatinine and glycemic traits including HbA1c." (PMID 38826208, 2024).
ARHGAP44 also shares sentences with these, for which no sentence is quoted: Anxiety (3 papers); phobia (2); AIDS (1); autism spectrum disorder (1); breast carcinoma (1); depression (1); diabetes (1); liver cancer (1); lung carcinoma (1); mood disorder (1); prostate carcinoma (1); psychosis (1).